INS (insulin)
Diseases named in the same sentence as INS in open-access papers (continued):
Sharing a sentence is not in itself a finding about the gene and the disease.
diabetes (continued). "Diabetes patients have aberrant insulin metabolic signaling, which reduces insulin-stimulated cardiac nitric oxide (NO) generation and endothelial nitric oxide synthase (eNOS) activity while increasing cardiomyocyte intracellular Ca2+/Ca2+ sensitivity and decreasing sarcoplasmic Ca2+ absorption." (PMID 37324738, 2023). "Diabetes mellitus is a metabolic syndrome characterized by hyperglycemia accompanied by alterations of fat, protein, and carbohydrate metabolism that results from defects in insulin secretion, reduced insulin action, or both." (PMID 36903291, 2023). "Importantly, children with residual β-cell function experience lower risk of severe hypoglycemia, have better blood glucose control, and lower insulin requirements, leading to better diabetes management." (PMID 37766096, 2023). "Diabetes mellitus (DM), caused by lack of insulin, insulin resistance, or both, is considered a risk factor for AD." (PMID 37034173, 2023). "Type 1 diabetes mellitus can be controlled with the external administration of insulin." (PMID 38139019, 2023). "Hence, defects in either beta cell mass or function, or both, can result in inadequate levels of plasma insulin that can effectively lower plasma glucose concentrations, leading to the onset of hyperglycemia and diabetes." (PMID 37242432, 2023). "Due to the fact that chlorogenic acid and flavonoids are present in bilberry leaves, it was checked whether the extract of the raw material would improve glucose homeostasis and insulin sensitivity in mice with obesity and diabetes." (PMID 37763199, 2023). "Diabetes is a chronic condition that occurs when there are raised levels of glucose in the blood because the body cannot produce any or enough of insulin or use insulin effectively." (PMID 37231408, 2023). "By 6 months, the UPI progeny had developed diabetes, which is similar to the type 2 diabetes observed in adults and is caused by a progressive lack of insulin synthesis and insulin activity." (PMID 37374343, 2023). "Metformin, the most commonly prescribed drug for diabetes, may also increase insulin sensitivity in peripheral tissues during fasting." (PMID 36771772, 2023). "Quercetin, given at doses of 15 mg kg/day for four weeks, has also been found to decrease blood sugar and raise the level of plasma insulin in rats with diabetes induced by administering streptozotocin and simultaneously improved bone mineral metabolism and structural bone matrix." (PMID 36986906, 2023). "Providers could refer any patient with type 1 or type 2 diabetes (using insulin) to use a DSC though participation from the people with diabetes was voluntary." (PMID 37535407, 2023). "Additionally, DACH1 suppresses pancreatic cell proliferation and is involved in diabetes insulin signaling." (PMID 37766305, 2023). "Over half (56.0%) used insulin entirely or partly for treatment of their diabetes." (PMID 37663636, 2023). "In addition, although the reported impacts of the pandemic on diabetes management vary by country and insulin treatment technology, multiple countries have reported an increase in diabetic ketoacidosis frequency and suboptimal glycemic variability." (PMID 36939680, 2023). "Among them, 7.4 million people with diabetes used at least one formulation of insulin." (PMID 36751859, 2023). "Pigs are also a valuable model for T1D research due to their physiological and anatomical similarities to humans, allowing researchers to study various aspects of diabetes, including pancreatic islet transplantation, insulin production, glucose metabolism, and immune responses." (PMID 38203514, 2023). "6: Insulin can reliably prevent long-term complications due to diabetes." (PMID 37654567, 2023). "However, in lymphocytes from patients with type 2 diabetes mellitus where insulin regulates glucose uptake and function, mitochondrial dysfunction has been observed." (PMID 36326284, 2023).
diabetes (continued). "The life-long burdens related to TP were illustrated in a recent study reporting that the psychosocial impact of diabetes, the need for insulin therapy, and the severity of exocrine insufficiency were all significantly greater after TP than after a Kausch-Whipple procedure." (PMID 36902800, 2023). "Additionally, clinical factors related to the severity of diabetes, including insulin use, endocrinology care, and diagnosis of diabetes complications were significantly associated with lower likelihood of achieving glycemic control." (PMID 37708338, 2023). "Underlying pathophysiological mechanisms for the hyperinsulinemia, insulin resistance, and prediabetes/diabetes in active acromegaly, are GH-mediated increased lipolysis, reduced peripheral glucose utilization, and enhanced gluconeogenesis by the insulin-antagonizing effects of GH." (PMID 36901984, 2023). "Upon its release in 1993, intensive insulin therapy was heralded as the new standard of care for all or most people with type 1 diabetes, although the study was limited to participants aged 13–39 years at entry with duration of diabetes of 1–15 years." (PMID 37794113, 2023). "Administration of selenium, at an average dose of 200 μg/d for 3 months, was shown to improve insulin sensitivity and reduce cardiometabolic risk in patients with diabetes with or without congestive heart failure and coronary heart disease." (PMID 36839303, 2023). "Although some recommendations vary across guidelines, CGM is consistently recommended for individuals with diabetes who are treated with intensive insulin regimens, with stipulation that treatment using CGM should be individualized and be offered to those who are willing and capable." (PMID 36761197, 2023). "One possible interpretation is that GIV controls the endocytosis of Nephrin to facilitate insulin secretion, which may be impaired in diabetes because of the downregulation of GIV in pancreatic β cells." (PMID 36822326, 2023). "Similarly, some authors classify any form of diabetes in pregnancy as a comorbidity, whereas OB-CMI only includes diabetes requiring insulin." (PMID 37856118, 2023). "Although eQTL or cASE analyses in human islets did not support the association between these additional genes and diabetes risk, the transcriptional regulator JQ1 lowered the expression of multiple genes at the SLC30A8 locus and enhanced stimulated insulin secretion." (PMID 37502937, 2023). "Dietary-induced diabetes leads to increased insulin secretion in the pancreases of zebrafish." (PMID 37569372, 2023). "Also, it should be considered that the number of patients on insulin was small to make any definite statements regarding the relationship between myocardial fibrosis and the type of medications for diabetes." (PMID 36765354, 2023). "The activation of high circulating levels of insulin and insulin-like growth factors among people with diabetes, both of which promote cell proliferation and affect cell apoptosis, has been linked with a higher risk of incident cancer, as well as cancer metastasis and recurrence." (PMID 37113731, 2023). "Pancreatic tissue sections from 15 non-diabetic, eight double autoantibody-positive and ten type 1 diabetic (0–2 years of disease duration) organ donors were obtained from the Network for Pancreatic Organ Donors with Diabetes, and stained for insulin, glucagon, CD3 and CD8 by immunofluorescence." (PMID 36884056, 2023). "Its administration to diabetes patients improved their insulin sensitivity." (PMID 35237941, 2023). "Additionally, stevioside has been found to increase insulin levels and improve insulin sensitivity, making it beneficial for individuals with diabetes." (PMID 37375718, 2023). "A previous study has reported that young people at increased familial risk of depression are likely to have diminished insulin sensitivity even without depressive symptoms, suggesting vulnerability to diabetes." (PMID 38125283, 2023).
diabetes (continued). "It is speculated that excessive napping disrupts the sleep-wake rhythm and increases sympathetic nerve activity during the day, resulting in decreased insulin sensitivity, which may be a mechanism leading to development of diabetes." (PMID 38027100, 2023). "In addition, the app offers the ability to store insulin ratios/doses and pump settings and enables the user to receive communications directly to the app from their diabetes team." (PMID 38136135, 2023). "Similarly, 90% (n=9) of users reported spending more time thinking about diabetes mellitus as a result of using the system and managing to dose insulin better." (PMID 37115601, 2023). "He reported a history of diabetes irregularly taking oral medications and insulin therapy." (PMID 37506152, 2023). "Diabetes status was defined by self-report of diagnosis or use of insulin." (PMID 36795065, 2023). "Accordingly, we believe that the impaired insulin response and diabetes- and prediabetes-specific serum lipoprotein patterns may further contribute to erroneous results for all these equations." (PMID 37240676, 2023). "Compared to patients in the first wave, patients in the second wave were more often obese, had more often comorbidities such as diabetes, chronic kidney disease, or neuromuscular disease, and were treated more frequently with systemic steroids, beta blocking agents, or insulin at home." (PMID 37445542, 2023). "Diabetes mellitus could weaken insulin signaling pathways in the regulation of the functions of neurons and glial cells." (PMID 37848819, 2023). "A 2020 study in Poland, the Czech Republic, and Slovakia using the ADDQoL instrument showed that three of the factors our study identified as predictors of lower HRQoL—lower levels of education, diabetes-related complications, and insulin usage—instead had a positive effect on quality of life." (PMID 37033039, 2023). "Anti-diabetes medications in particular sodium-glucose co-transporters-2 inhibitors and glucagon-like peptide agonists were shown to induce diabetes remission in particular when combined with other therapies including insulin." (PMID 36829204, 2023). "Insulin resistance (IR) is a state of reduced responsiveness of target cells or the whole organism to the insulin concentrations to which they are exposed, usually preceding the onset of diabetes, and has been identified as a key mediator of diabetes as well as cardiovascular disease." (PMID 37138277, 2023). "The treatment protocol included diabetes compensation (treatment with fractional insulin therapy), anticoagulant, metabolic therapy and angiotropic therapy, physical treatment methods, osteoporosis therapy with calcium preparations, and wound-specific interventions." (PMID 37900068, 2023). "The mRNA expression levels of PTEN and GSK-3β were significantly increased, while IRS-1, PI3k, Akt, and GLUT-2 were decreased considerably in the DC group compared to the NC group (p < 0.001), demonstrating the dysregulation of the insulin-mediated PI3K/AKT pathway in diabetes." (PMID 38231654, 2023). "Participants also requested additional help with accessing physicians to discuss medications such as insulin, as well as diabetes comorbidities such as hypercholesterolemia: “We wanted to have diabetes doctors at screenings to provide more direct care at the churches." (PMID 36817737, 2023). "One endocrinologist (male) stated “people with diabetes are most concerned about their A1C, and they get A1C, and thus talking about improving exercise and eating can be framed in a way that promotes improving A1C and insulin sensitivity." (PMID 37614408, 2023). "During Period 1, the variables “diabetes”, “use of IV insulin”, “use of SC insulin”, “SOFA score” and time slots “16-20 h” and “20-0 h”, were significantly associated with higher blood glucose level, and the variable “ongoing infection” was significantly associated with lower blood glucose levels." (PMID 37330419, 2023).
diabetes (continued). "Therefore, improving patients’ perceptions and acceptance of insulin should be a primary goal of diabetes care." (PMID 37143082, 2023). "This may result in a range of metabolic profiles with varying degrees of insulin sensitivity among frail older people with diabetes." (PMID 37367862, 2023). "The antibiotic streptozotocin, which is generated by the bacterium Streptomyces achromogenes, is commonly used to cause diabetes in insulin-dependent as well as non-insulin-dependent animals." (PMID 37936909, 2023). "However, when castrated, there is a reduction in the number of diabetes cases as a result of insulin antagonism during the diestrus phase." (PMID 36830471, 2023). "According to the generally accepted definition, diabetes mellitus is defined as a group of heterogeneous metabolic disorders which are caused by an impaired or absent insulin secretion, with a common feature being elevated blood glucose levels." (PMID 37373398, 2023). "In conclusion, we identified NECAB1 as a negative regulator of insulin secretion, and induction of NECAB1via GR activation may mediate pancreatic β-cell dysfunction in some contexts such as obesity-related diabetes mellitus." (PMID 37863964, 2023). "Similarly, the relationship between CpG methylation pattern of the proximal insulin gene promoter and diabetes had been reported." (PMID 36875456, 2023). "To assess causality of the identified biomarkers we would ideally have tested against the genetics of time to insulin requirement in people with diabetes, but in the current study the outcome was underpowered (n = 14,000) and there is no publicly available data for time to insulin genetic variants." (PMID 37137910, 2023). "In early 2017, he was also diagnosed with diabetes and started on insulin-hypoglycemic treatment." (PMID 37637036, 2023). "It is believed that with the continuous deepening of research, the mechanism of sphingolipids’ involvement in insulin resistance and the mechanism of brain lesions will become clearer, which will bring new targets and hope for the treatment of diabetes, AD, PD, tumor and other related diseases." (PMID 37867511, 2023). "Although the central theme of T2D is highlighted as insulin resistance and hyperglycemia, several disorders in diabetes patients tend to be partially insulin responsive and therefore the glycemic aspect in the case of diabetes is just one part of a deranged metabolic network." (PMID 37894760, 2023). "Previous research has shown that conventional treatment of diabetes, whether using insulin or oral hypoglycemic medications, can have serious side effects and is ineffective in preventing the onset of numerous complications related to diabetes." (PMID 37895159, 2023). "The observed insulin resistance and diabetes in Cd-exposed subjects was shown to be secondary to Cd’s ability to alter both the insulin signaling cascade and induce β-cell dysfunction and impaired insulin secretion." (PMID 37624175, 2023). "Diabetes is a metabolic disorder and is characterized by chronic hyperglycemia with altered metabolism of carbohydrates, proteins, and fats resulting from altered insulin secretion, action, or both." (PMID 36677055, 2023). "Understanding these activation mechanisms may aid in the development of novel therapeutic strategies for diabetes and other insulin-related disorders." (PMID 37779149, 2023). "FOXO and PI3K-AKT signaling are involved in lipid metabolism and insulin signaling and may be shared pathways between diabetes and AD." (PMID 36982982, 2023). "It is crucial to acknowledge that the heterogenicity of these studies, including variations in outcomes, patient population, sample size, methods of glycemic monitoring, and insulin delivery restricts the clear interpretation of telemedicine’s role on diabetes management." (PMID 37685740, 2023). "Notably, these specialized diets also have the added benefit of reducing the need for insulin, thereby offering a more holistic approach to diabetes management." (PMID 37836433, 2023).
diabetes (continued). "Type 2 diabetes mellitus (T2DM) is a chronic disease characterized by a prolonged hyperglycemic state caused by a combination of underlying defects, which include insulin tolerance in muscle and liver and reduced insulin production by pancreatic β cells." (PMID 37175783, 2023). "Insulin analogs are considered safe and efficient for treating diabetes in pregnancy." (PMID 38138975, 2023). "Multicollinearity analyses revealed that the tolerances of the history of diabetes and antidiabetic drugs or insulin prescriptions were smaller than 0.2, and the VIFs were larger than 5, confirming that the regression models were affected by the presence of multicollinearity." (PMID 37034347, 2023). "Currently, dapagliflozin, a sodium–glucose cotransporter 2 inhibitor (SGLT2i), is recognized as a novel treatment for both type 1 and type 2 diabetes, and is used as an additional therapy to insulin to improve glycemic control and prevent complications of diabetes." (PMID 37424302, 2023). "Maturity-onset diabetes of the young (MODY) comprises approximately 1%–5% of all diabetes cases, demonstrating typical features including early onset, a familial history of diabetes inherited in an autosomal dominant pattern, and being non-insulin-dependent." (PMID 37711893, 2023). "In the present study, patients with poor glycemic control were more likely to be prescribed a combination of OHAs and insulin, indicating the need for higher doses or additional treatment as an attempt to provide better glycemic control for the deteriorations of diabetes over time." (PMID 37008178, 2023). "Therapy for this type of diabetes involves exogenous insulin administration." (PMID 37110171, 2023). "A successful pancreas transplant, unlike intensive insulin regimen, restores euglycemia without the risk of hypoglycaemia and halts or reverses the progression of secondary complications of diabetes." (PMID 37266028, 2023). "Comparing the diabetic groups treated with insulin, the immunomodulatory effect of okra on diabetes may be easily clarified." (PMID 38046568, 2023). "As discussed in our original review, we speculate that chronic insulin use can be seen as an indicator of more severe diabetes." (PMID 37204441, 2023). "Thus, there is a possibility that repeating c-peptide levels and insulin antibodies would help uncover patients with T1DM or LADA or ketosis-prone diabetes that were misclassified as Type II." (PMID 37441367, 2023). "DKA is often multifactorial and may be triggered by factors such as infection, poor adherence to insulin therapy, pump failure, difficulties at injection/pump sites in addition to newly diagnosed diabetes." (PMID 37840692, 2023). "We report that patients carrying protective INS have a further reduced risk of developing diabetes complications compared to those lacking this gene variant." (PMID 36701305, 2023). "The multifaceted pharmacological activities of these compounds, including their ability to modulate glucose metabolism, enhance insulin sensitivity, and mitigate diabetes-related complications, make them attractive candidates for further exploration and development." (PMID 37763235, 2023). "In contrast, a sample of 940 individuals with diabetes from Itabuna aged 60.8 + 11.4 years, with average diabetes duration of 10.4 years, reported use of insulin in 25.8%; more than mild DR was present in 25.7%; and educational level was up to elementary school in 54.4%." (PMID 37430345, 2023). "Although strict glucose management with insulin can prevent or even eliminate the long-term consequences of diabetes mellitus, an insulin overdose may lead to fatal hypoglycemia." (PMID 37965322, 2023). "Furthermore, previous research has highlighted the therapeutic potential of strontium nanoparticles in addressing diabetes-related physiological changes by regulating insulin release in high-fat diet-induced Drosophila models." (PMID 38292989, 2023).